TF (transferrin)
Diseases named in the same sentence as TF in open-access papers (continued):
Sharing a sentence is not in itself a finding about the gene and the disease.
anemia (continued). "Anemia and iron status are mainly assessed with Hb and ferritin since measurement of transferrin saturation (TSAT) or other blood markers of anemia are not widely available in the everyday clinical practice in Greece." (PMID 34187376, 2021). "Second, we did not measure other biomarkers of anemia, including serum iron, ferritin, and transferrin levels." (PMID 33568084, 2021). "Transferrin levels and soluble transferrin receptor were not different between the groups, discarding subclinical anemia." (PMID 34065056, 2021). "As transferrin and serum iron concentrations are the basis for TSAT calculations, low transferrin levels may result in TSAT > 20%, which shows the limitations of the anemia of inflammation definition." (PMID 34677368, 2021). "Unexplained anemia with low transferrin saturation and high ferritin levels without inflammation should prompt the suspicion of aceruloplasminemia, which can be easily confirmed by low serum ceruloplasmin levels." (PMID 32235485, 2020). "In this study, patients in the transfusion group had higher levels of inflammatory biomarkers, such as IL-6 and ferritin, as well as lower TIBC and transferrin levels as biomarkers of anemia, upon ICU admission than those in the non-transfusion group." (PMID 30673726, 2019). "As collateral findings, we stress that ferritin and transferrin levels, markers of both inflammation and iron status, did not impact on the ESRD-linked anaemia in this population." (PMID 31137583, 2019). "Anemia and iron status parameters were low in a considerable number of patients before surgery, as follows: hemoglobin 20%, mean corpuscular volume (MCV) 48%, ferritin 28%, serum iron 51%, and transferrin saturation 60%." (PMID 29324643, 2018). "The coefficient beta of the linear regression model showed that ferritin and transferrin had a negative effect on hemoglobin concentration in patients with anemia." (PMID 29801478, 2018). "The ferritin concentration (ng/ml) increased significantly in patients with no-anemia and the transferrin concentration (mg/dl) in patients with anemia." (PMID 29801478, 2018). "In turn, the levels of ferritin and transferrin are not sufficiently accurate, as they are both elevated in any anemia of inflammation." (PMID 25311752, 2015). "The persistence of anemia may result from a dysfunctional EPO or from reduced iron availability, as suggested by the low serum iron and transferrin levels." (PMID 25867633, 2015). "The CRF rats present persistent anemia, without EPO deficiency, with low serum iron and transferrin levels, although iron storage was normal, and unchanged serum IL-6 and hsCRP levels, showing the absence of systemic inflammation." (PMID 26712750, 2015). "That indicated such increase of TF and CP was not the result of inflammatory or anaemia but a phenomenon unique to PAB." (PMID 26099594, 2015). "None of them presented anemia, but most of the individuals showed transferrin saturation below the normal range (< 20%) and all of them showed low serum ferritin levels." (PMID 25351758, 2014). "In particular, two ID stages can be distinguished: (a) initial, characterized by reduced transferrin saturation but without anemia; and (b) advanced, when microcytic, hypochromic iron-deficiency anemia (IDA) becomes evident." (PMID 24795637, 2014). "Such a circumstance would be where pH and the anion gap are altered, such as within a hypoxic environment and hypophosphatemia, or when apo-TF and/or APP/sAPPα are in limited supply, such as with anemia of chronic inflammation and Alzheimer’s disease respectively." (PMID 25464026, 2014). "Blood tests revealed mild anemia, moderate renal insufficiency (glomerular filtration rate (GFR): 56 ml/min), prediabetes (glycated hemoglobin (HbA1c) 6.3), reduced transferrin saturation (9%), elevated transferrin (381 mg/dl), increased total iron binding (537 mg/dl), and hypertriglyceridemia." (PMID 37303410, 2023).
anemia (continued). "Due to the lack of data on markers of iron status (serum iron, ferritin, and transferrin), hepcidin, or erythropoietin, we could not assess the precise mechanisms of anemia in the included study population." (PMID 36008838, 2022). "We did not measure the iron status and iron indicator such as serum ferritin and transferrin in this study; therefore, we could not conclude the effects of different types of anemia on childhood anemia." (PMID 35458183, 2022). "Since FTH1/FTL (ferritin) and TF (transferrin) are not sufficiently accurate, as they are both elevated in any anemia or inflammation process, the ferritin index (ratio of soluble TFRC to log ferritin) has been suggested as a more stable, reliable and sensitive marker." (PMID 35327526, 2022). "Thus, our suggested mechanism for anaemia in ESRD patients is that an increased level of TTR could induce TTR aggregates, inhibiting transferrin endocytosis, this, in turn, decreases intracellular iron, reducing erythropoiesis and leading to anaemia." (PMID 32994444, 2020). "Also, the best way to diagnose anemia of chronic disease is to prove a mild or moderate decrease of hemoglobin with normocytic normochromic erythrocytes, low serum iron, and TIBC with normal transferrin saturation, as well as normal or elevated ferritin." (PMID 30984307, 2019). "Interestingly, the knock-in model Tfr2KI, specifically lacking the beta-isoform, is characterized by normal transferrin saturation, liver iron concentration, hepcidin and Bmp6 levels but show a transient anemia at young age." (PMID 24847265, 2014). "Third, due to the lack of data on markers of iron status (serum iron, ferritin, and transferrin), hepcidin, or erythropoietin, we could not assess the mechanisms of anemia in our study population." (PMID 24878740, 2014). "Moreover, the expression of bone morphogenetic protein-6 (BMP-6), a secondary mediator of chronic inflammation anemia, did not exhibit any change, neither did the major iron carrying protein produced by the livers, transferrin." (PMID 24324805, 2013). "Finally, another limitation of this study is that other iron-related biomarkers, such as free iron, transferrin, and transferrin saturation, were not analyzed, since the focus of our study was rather on infection and acute phase biomarkers than anemia or other iron metabolism disorders." (PMID 35741214, 2022). "Hpx/hpx mice absorb somewhat more iron relative to β-thalassemic mice, which have a comparable anemia and reticulocytosis, suggesting that not the hemoglobin levels but the amount of transferrin itself, relative to the degree of erythropoietic demand, may influence hepcidin expression." (PMID 20631898, 2010). "According to hemoglobin, ferritin, and transferrin saturation concentrations patients were assigned to a Control group (no anemia, no ID), ID group (no anemia, ID), IDA group (anemia, ID) or Others group (anemia, no ID)." (PMID 39863874, 2025). "The combination of low transferrin saturation, high ferritin, normal transferrin receptor levels, and elevated CRP in these patients suggests anemia of chronic disease rather than classic IDA." (PMID 39863874, 2025). "There was a statistically significant difference in the mean value of serum ferritin, serum TIBC, and transferrin saturation when compared between MAM and SAM children with no anemia, respectively (p-value=0.013, p-value=0.029, p-value=0.025)." (PMID 39205775, 2024). "Additionally, information about diet during the follow-up, anemia-related data including mean corpuscular volume, mean corpuscular hemoglobin, mean corpuscular hemoglobin concentration, serum iron, transferrin, and ferritin were lacking, which might influence the interpretation." (PMID 34357115, 2021). "Our data can only provide indirect information on the etiology of anemia from hemoglobin and MCV, since no parameters of iron metabolism like ferritin, transferrin saturation, or soluble transferrin receptor were obtained by the registry." (PMID 29358946, 2017).
anemia (continued). "In cross-sectional analyses, adjusting for maternal blood lead level at delivery and child’s concurrent anemia status, the relationship between genotype (either HFE or TF) and blood lead level (at any age) was non-significant (data not shown)." (PMID 18795173, 2008). "When preoperative parameters were compared between patients with anemia and non-anemic patients, patients with anemia were on average significantly older, had higher C-reactive protein (CRP) concentrations, lower transferrin and lower transferrin saturation." (PMID 35895618, 2022). "Abnormal laboratory parameters include: decreased transferrin; ceruloplasmin; increased ferritin (non-specific, > 800 ng/mL); mixed hyperbilirubinaemia; low aminotransferases; low factors V and VII (< 10% of normal); thrombocytopenia, anaemia and increased alpha-fetoprotein (> 200 ng/mL)." (PMID 21092086, 2010).
iron overload (196 papers, 2006 to 2026). "Elevated ferritin and transferrin saturation and exclusion of secondary causes should prompt genetic evaluation for hereditary disorders predisposing iron overload." (PMID 42083434, 2026). "Iron overload accounts for less than 10% of individuals with hyperferritinaemia, and when present is usually associated with an elevated serum transferrin saturation above 45%." (PMID 40013463, 2025). "Although homozygosity for the H63D mutation results in elevated intracellular iron and serum markers (ferritin, transferrin saturation), it rarely leads to clinical iron overload, unless combined with other mutations." (PMID 40941762, 2025). "Clinically, serum iron overload (indicated by high ferritin levels and high transferrin saturation) is associated with poor functional outcomes in patients." (PMID 39396974, 2024). "Recently, transferrin saturation has come to be regarded as an indicator of iron overload, with thresholds suggested by the European Association for the Study of the Liver (EASL) guidelines." (PMID 39262540, 2024). "Iron overload usually manifests as high ferritin and transferrin saturation that indirectly causes insulin resistance through liver injury and lipid metabolism abnormalities." (PMID 37904845, 2023). "Our MR results provide evidence for a causal role of AUD in increasing serum iron and transferrin saturation, a sensitive marker of iron overload." (PMID 35834561, 2022). "Iron overload and deficiency of transferrin (TF) have been found in EMs-related infertile patients follicular fluid (EMFF)." (PMID 35787614, 2022). "Extremely rare causes of primary iron overload include genetic defects of the iron metabolism caused by variants in the ceruloplasmin and transferrin gene." (PMID 34067164, 2021). "Some authors have reported that severe iron overload itself was detrimental, but also that toxic non-transferrin-bound iron caused by conditioning was associated with tissue damage." (PMID 33602150, 2021). "Only a few patients with identified heterozygous HFE variants had elevated ferritin and saturation of transferrin > 45%, which is indicative of iron overload." (PMID 34349782, 2021). "Systemic iron overload associates with elevated serum ferritin and normal or mildly elevated transferrin saturation." (PMID 32625166, 2020). "In patients with sickle cell disease, the increase in both ferritin and transferrin saturation has been associated with iron overload, hepatic, myocardial and endocrine organs dysfunctions, as well as severity, morbity, and mortality of the disease." (PMID 31366068, 2019). "Patients develop moderate to severe iron overload, mostly in tissue macrophages but also parenchymal cells, which is associated with low transferrin saturation and serum iron." (PMID 30420953, 2018). "Aceruloplasminemia and atransferrinemia are further inherited disorders of iron overload caused by deficiency in ceruloplasmin or transferrin, the plasma ferroxidase and iron carrier, respectively." (PMID 30420953, 2018). "Although it has similar clinical features and phenotypic hallmarks to other forms of hereditary hemochromatosis (high transferrin saturation, parenchymal iron overload, macrophage iron deficiency), it is transmitted in an autosomal dominant fashion." (PMID 30420953, 2018). "Loss-of-function ferroportin mutations lead to ferroportin disease, characterized by iron overload in macrophages and low transferrin saturation." (PMID 30420953, 2018). "In agreement with previous studies of mice with genetically caused iron overload, we therefore assumed that the binding capacity of transferrin is saturated in iron loaded animals and NTBI is found in the serum." (PMID 28068331, 2017). "In conditions of iron overload, high levels of plasma iron are associated with the presence of non-transferrin bound iron (NTBI), which can be efficiently taken up by tissues." (PMID 29089902, 2017).
iron overload (continued). "Diagnostic accuracies of LICSIR, R2 and serum transferrin, transferrin-saturation, and ferritin compared to increased R2* (≥44 Hz) as indicator of iron overload were assessed using ROC-analysis." (PMID 27431019, 2016). "In 2001, our group showed that hyperferritinemia with normal transferrin saturation was a hallmark of a glucose/lipid metabolism disorder and, when associated with multiple metabolic abnormalities and iron overload, identified patients at risk for NASH." (PMID 27077854, 2016). "Likewise, elevated levels of serum transferrin, as a response to iron overload, have been associated with an unfavorable prognosis by promoting the induction of ferroptosis." (PMID 38921441, 2024). "A transferrin saturation (TSAT) greater than 45% is generally considered an appropriate threshold for suspecting iron overload caused by increased intestinal iron absorption and is the first and indispensable test in differential diagnosis of hyperferritinemia." (PMID 36768886, 2023). "Alterations of genes involved in iron metabolism and transport such as DMT1 or transferrin may cause rare forms of chronic and often severe congenital anemia with iron overload and a reduction of iron available for erythropoiesis." (PMID 36986429, 2023). "Furthermore, the combined therapy of L1 and THC causes non-transferrin-bound iron (NTBI) reduction in a condition of systemic iron overload (lowering blood pressure and improving baroreflex and vascular reactivity)." (PMID 36014335, 2022). "Hypotransferrinemia with low transferrin concentrations also causes systemic iron overload and is characterized by impaired erythropoiesis and microcytic anemia due to the marked reduction in iron delivery to bone marrow, which, in turn, increases iron absorption." (PMID 34067164, 2021). "Nevertheless, transferrin saturation might be a useful biomarker for identifying patients with iron overload, which is also a risk factor for CRA." (PMID 34439443, 2021). "However, iron supplementation can cause iron overload, occurring typically when the plasma iron content exceeds the iron-binding capacity of transferrin." (PMID 22203913, 2011). "It has been suggested that H63D homozygotes have a slight risk of iron overload, therefore, regular monitoring of the biochemical indices of iron overload (ferritin and transferrin saturation levels) may be suggested." (PMID 17134494, 2006). "The individual may be at risk of developing iron overload/HH and it is recommended that the indices of iron overload (transferrin saturation, ferritin) be regularly monitored." (PMID 17134494, 2006). "Iron enters the brain either bound to transferrin (Tf), which allows iron to pass through the blood–brain barrier or the blood–cerebrospinal fluid barrier, or possibly unbound, particularly in circumstances where transferrin gets saturated with iron and causes iron overload." (PMID 39770511, 2024). "Median transferrin saturation (TS), median serum ferritin (SF), and provisional iron overload prevalence were higher in p.C282Y/p.C282Y (p ≤0.0001, each comparison)." (PMID 41542669, 2026). "Four patients had iron overload resolution at 32 weeks (mean [SD] transferrin saturation, 32.9% [10.1%]), 1 had resolution at 40 weeks (transferrin saturation, 47.6%), and 1 had resolution at 52 weeks (transferrin saturation, 39.7%)." (PMID 41155315, 2025). "LPI appeared to correlate significantly with transferrin saturation, supporting the theory that it arises from iron overload." (PMID 40650208, 2025). "Iron overload pathophysiology is defined by the saturation of the principal iron transport protein, transferrin, with the consequential appearance of non-transferrin-bound iron (NTBI) in plasma." (PMID 40656262, 2025). "For instance, during iron overload, TF saturation results in enhanced circulation of non-transferrin-bound iron (NTBI), a potentially toxic form of iron." (PMID 41007630, 2025).